RB1 (RB transcriptional corepressor 1)
Diseases named in the same sentence as RB1 in open-access papers (continued):
Sharing a sentence is not in itself a finding about the gene and the disease.
diabetes (continued). "Of note, Rb1 required both Nrf2 and PGC-1α to ameliorate diabetes-accelerated atherosclerosis in rodents without affecting metabolic parameters, suggesting that the benefit of Rb1 in diabetic atherosclerosis was independent of alterations in glucose and lipid metabolism." (PMID 36163178, 2022).
medulloblastoma (12 papers, 2003 to 2025). A malignant, invasive embryonal neoplasm arising from the cerebellum. "Consistent with the data, the signatures of tumor DEGs induced by rb1 somatic inactivation were closely associated with those of human medulloblastomas and PNETs." (PMID 28903419, 2017). "The complicating factor that both medulloblastoma and pinnal tumors arise in the same model, can be addressed by maintaining Rb1 wild-type." (PMID 35468745, 2022). "Tumors induced by rb1 somatic inactivation were characterized as medulloblastoma-like primitive neuroectodermal tumors based on incidence location, histopathological features, and immunohistochemical tests." (PMID 28903419, 2017). "Tumors induced by rb1 somatic inactivation displayed medulloblastoma like PNET characteristics in histopathology and immunohistochemistry analysis." (PMID 28903419, 2017). "There were 57 up-regulated genes common to the tumors induced by rb1 somatic inactivation (zebrafish tumors) and human medulloblastomas and PNETs most of which were involved in cell cycle progression and mitosis (such as cdk1, aurka, plk1, etc.)." (PMID 28903419, 2017). "A recent report showed that in glial cells of transgenic mice, overexpression of E2F1, a transcription factor downstream of rb1 pathway, also resulted in the induction of medulloblastomas and other PNETs." (PMID 28903419, 2017). "Although rb1 mutation has not been widely detected in traditional human medulloblastomas, some reports from clinical case studies and animal tumor models have suggested that rb1 pathway participates in medulloblastoma development." (PMID 28903419, 2017). "It will therefore be interesting to analyse a possible role of the RB1 pathway in medulloblastoma subtypes D and E with photoreceptor-specific gene expression." (PMID 18769486, 2008). "Taken together these data indicate that tumors from rb1-TALENs injected tp53e7/e7 mutant zebrafish may be medulloblastoma-like PNETs based on their incidence location, histopathological features, and neuronal/neural characteristics from immunohistochemistry." (PMID 28903419, 2017). "Moreover, public microarray data of human medulloblastomas and PNETs were used to compare gene expression profiles of tumors induced by rb1 somatic inactivation." (PMID 28903419, 2017). "Although RB1 mutations have never been detected in other medulloblastomas, some experimental tumor models suggest a role for the RB pathway in this tumor." (PMID 18769486, 2008). "Hence, we could conclude that tumors induced by rb1 somatic inactivation are medulloblastoma-like PNETs." (PMID 28903419, 2017). "However, aberrations in RB1 and MYC/MYCN as well as leptomeningeal dissemination are characteristics of embryonal tumors as medulloblastomas or atypical teratoid rhabdoid tumors." (PMID 33876327, 2021). "According to several reports, medulloblastoma is classified into four molecularly distinct subgroups –WNT, SHH, Group C (MYC activated), and Group D. Zebrafish tumors induced by rb1 somatic inactivation displayed an apparent up-regulation of genes in neural development and NOTCH pathway." (PMID 28903419, 2017).
medulloblastoma (continued). "Therefore, we inferred that zebrafish tumors induced by rb1 somatic inactivation are a primitive type of medulloblastoma-like PNET accompanied by indistinguishable subtypes." (PMID 28903419, 2017).
large cell neuroendocrine carcinoma (11 papers, 2012 to 2026). A usually aggressive carcinoma composed of large malignant cells which display neuroendocrine characteristics. "While the neuroendocrine phenotype and common occurrence of RB1 loss in large cell neuroendocrine carcinoma of the lung (LCNEC) have suggested potential ties between this cancer type and SCLC, a robust mouse model of LCNEC development has not yet been developed." (PMID 32747478, 2020).
metastatic prostate carcinoma (11 papers, 2011 to 2025). A carcinoma that arises from the prostate gland and has spread to other anatomic sites.
pituitary adenomas (11 papers, 2003 to 2025). "The established role of RB1 in inhibiting invasive growth makes it a key gene of interest in studies aiming to uncover risk factors for aggressive pituitary adenomas." (PMID 39859246, 2025). "At present, hypermethylation is accepted as a mechanism of RB1 gene inactivation and, in pituitary adenomas, loss of pRB expression has been found to be associated with methylation of the CpG island within the RB1 promoter region together with deletion within the protein-binding pocket domain." (PMID 12556968, 2003).
spindle cell lipoma (11 papers, 2014 to 2025). A benign circumscribed tumor composed of spindled cells, adipocytes, and collagen bundles. "At the molecular level, spindle cell lipoma is associated with monoallelic or biallelic deletions of 13q13, affecting RB1, leading to loss of RB1 expression on immunohistochemistry." (PMID 41246635, 2025). "At the molecular level, ASCPLT shares RB1 loss with spindle cell lipoma but typically harbors additional deletions, such as RCBTB2 loss." (PMID 41246635, 2025). "This case highlights the diagnostic challenges of differentiating LLTs from spindle cell lipomas (SCLs), particularly in the context of pRB deficiency and RB1 deletion." (PMID 41230282, 2025). "On the other hand, immunohistochemical staining for RB1 showed that nuclear RB1 expression was deficient in all examined spindle cell lipomas, pleomorphic lipomas, and cellular angiofibromas, as well as in 17 of 19 (89%) mammary-type myofibroblastomas." (PMID 28193293, 2017). "Genetic testing by FISH revealed a loss of RB1 (13q14-) in our tumor, which is described in spindle cell lipoma, (extra-) mammary myofibroblastoma, and cellular angiofibroma." (PMID 25105048, 2014). "The diagnosis was supported by FISH, which revealed monoallelic loss of RB1/13q14 region, as seen in spindle cell lipoma, (extra-) mammary myofibroblastoma, and cellular angiofibroma." (PMID 25105048, 2014). "The combination of cervical localization, variable spindle cell histology, CD34 positivity, and loss of RB1 immunoexpression places branchioma, spindle cell lipoma (SCL), and spindle cell–predominant trichodiscoma (SCPT) in the most common differential diagnosis." (PMID 37401932, 2023). "In ambiguous cases, molecular testing such as fluorescence in situ hybridization (FISH) can be valuable for detecting RB1 gene deletion in spindle cell lipomas." (PMID 40729281, 2024). "This group of tumors is now called atypical spindle cell lipoma, since it has a different genetic background, relating it to spindle cell lipoma, with deletion of the Rb-1 gene." (PMID 33799733, 2021). "In addition, about 90% of cases shows a loss of nuclear RB1 expression and the 13q14 deletion by F.I.S.H., confirming that MFB is pathogenetically related to other benign mesenchymal tumours showing a loss of 13q14, including spindle-cell lipoma and CAF." (PMID 35204448, 2022). "Because the expression levels of RB1 were not significantly reduced and because no mutations were seen by sequencing, the authors concluded that there is no decisive support for RB1 as the main target for the 13q deletions in spindle cell lipomas." (PMID 28193293, 2017). "For the 2 tumors with thick-walled blood vessels where spindle cell lipoma was considered in the histologic differential at the time of this review (patients 2 and 5), CD34 was negative and RB1 was retained in the adipocyte and stromal nuclei." (PMID 37131332, 2024).
atherosclerosis (10 papers, 2017 to 2025). A disease characterized by the build-up of fatty material and calcium deposition in the arterial wall resulting in partial or complete occlusion of the arterial lumen. "Prior to investigate the direct impact of Rb1 on NETs-induced endothelial activation, we evaluated the pharmacological effects of Rb1 treatment on atherosclerosis-associated endothelial activation in the HFD-fed Apoe−/− mice in vivo." (PMID 40771928, 2025). "In conclusion, the present study reveals that Rb1 mitigates NETs-induced aberrant endothelial activation in atherosclerosis." (PMID 40771928, 2025). "The work here demonstrates that Rb1 mitigates atherosclerosis in part by suppressing NETs-induced endothelial activation." (PMID 40771928, 2025). "To address these questions, we evaluated the pharmacological impact of Rb1 on NETs-induced endothelial activation in the pathological context of atherosclerosis." (PMID 40771928, 2025). "Meanwhile, further studies are necessary to identify specific downstream m6A targets that are modified by Rb1 treatment in the NETs-stimulated endothelial cells in the context of atherosclerosis." (PMID 40771928, 2025). "Rb1 administration promoted atherosclerotic plaque stability along with increased macrophage autophagy and M2 phenotype in the atherosclerosis model in ApoE−/− mice." (PMID 37304947, 2023). "There is a significant reduction of the relative en face atherosclerotic lesion area as well as the cross sectional lesion size at the aortic root, which demonstrated that the extent of atherosclerosis was significantly decreased in Rb1 treated mice." (PMID 34124194, 2021). "Apart from a series of benefits, Rb1 also shows powerful vascular‐protective potential 13, 14, 15, but its effect on atherosclerosis and detailed mechanisms needs further elucidated." (PMID 28944992, 2018). "We also validated the anti‐atherosclerosis effect in atherosclerotic ApoE−/− mice with Rb1 treatment in vivo." (PMID 28944992, 2018). "To explore the mechanism by which Rb1 protected against atherosclerosis, we next investigated the M1/M2 macrophage polarization in atherosclerotic lesions." (PMID 28944992, 2018). "Our study provides new experimental evidence for possibility of Rb1 in prevention and treatment of atherosclerosis." (PMID 28944992, 2018). "Our study provides new evidence for possibility of Rb1 in prevention and treatment of atherosclerosis." (PMID 28944992, 2018). "Considering the protective role of Rb1 in cardiovascular disease, we hypothesized that Rb1 may protect the progression of atherosclerosis by reversing resistin induced VSMCs dysfunction and oxidative stress." (PMID 37304947, 2023). "However, the modulation of atherosclerosis progression by Rb1 was inhibited by overexpression of miR-33." (PMID 34124194, 2021). "miR-33 overexpression attenuated the beneficial effects of Rb1 on atherosclerosis." (PMID 34124194, 2021). "Considering the anti-angiogenic role of Rb1, average number of vasa vasorum in adventitia surrounding the atherosclerosis plaques in aortic roots were counted to uncover whether Rb1 could inhibit neovascularization in apoE−/− mice." (PMID 34124194, 2021). "Rb1 can benefit myocardial ischemia, atherosclerosis/vascular dysfunctions, or other related diseases, suggesting the potential safety of Rb1 in cardiovascular functions, despite its action on β3AR." (PMID 31680950, 2019). "Thus, the present study was designed to further investigate the protective role of Rb1 against atherosclerosis using the well-defined classical ApoE-/- mouse atherosclerotic model." (PMID 30413028, 2018). "Considering the important role of macrophage polarization in inflammation and atherosclerosis, we propose the hypothesis that Rb1 may protect against atherosclerosis by skewing macrophage to the anti‐inflammatory M2 phenotype." (PMID 28944992, 2018).
atherosclerosis (continued). "Ginsenosides such as Rd and Rb1 have been reported to affect macrophage polarization and atherosclerosis progression; however, there has been no related research on diabetic atherosclerosis." (PMID 29867472, 2018).
Li-Fraumeni syndrome (10 papers, 2016 to 2025). "Associated with Li-Fraumeni syndrome, numerical chromosomal aberration, and inactivation of the RB1 tumor suppressor gene." (PMID 39735679, 2025).
lung squamous cell carcinoma (10 papers, 2015 to 2026). "However, the wild-type RB1 existence should also be taken into consideration, for instance, the IC50 value of SKPin C1 in lung squamous cell carcinoma cell line H520 with wild-type RB1 was higher than that in SCLC cell line H69 with deficient RB1." (PMID 37089937, 2023).
ovarian tumors (10 papers, 2013 to 2025). "A lower expression of RB1 mRNA was found in the ovarian tumours compared to normal tissue (p = 0.01)." (PMID 38612869, 2024). "Thus, to confirm that the ovarian tumor phenotype arises due to Rb1 inactivation in the germline, we conducted two experiments." (PMID 26176933, 2015). "Indeed, loss-of-function mutations in the Rb1 gene have been reported in non-teratoma human ovarian tumors that are somatic cell or germ cell in origin." (PMID 26176933, 2015). "Likewise, genes frequently amplified (MYC, PIK3CA and AURKA) or lost (RB1, PTEN) in ovarian tumours were also commonly multiplied or lost in our set of patient cells." (PMID 29180611, 2017).
retinal cancer (10 papers, 2010 to 2025). A malignant neoplasm involving the retina. "From the three family members, RB1 has been the most studied gene since it participates in tumor onset and progression, while RBl1 and RBl2 rarely display mutations in human retinal cancer." (PMID 32664691, 2020). "Indeed, functional loss of both alleles of the RB1 tumor suppressor gene results in >40,000-fold increase in predisposition to retinal cancer during childhood, while one constitutional RB1 mutant allele confers a broader but much lower cancer predisposition later in life." (PMID 20421947, 2010).
retinal tumors (10 papers, 1997 to 2025). "Retinal tumors, a type of cancerous eye malignancy commonly found in children, have long been linked to the RB1 variant." (PMID 41002743, 2025). "RB is a childhood retinal tumor, caused by the inactivation and loss of RB1 protein." (PMID 35356205, 2022). "Establishing stable, inducible rb1 transgenic lines to rescue developmental deficits will therefore be required to monitor juvenile and adult zebrafish for retinal tumors." (PMID 23209449, 2012).
serous carcinoma (10 papers, 2015 to 2025). "RB1 loss was a characteristic of high-grade serous carcinomas, and potentially limited postulated CDK4/6 actionability in some high-grade serous carcinoma patients." (PMID 33947352, 2021). "RB1 loss could be a mechanism of resistance to MEK inhibitors in RAS-mutated low-grade serous carcinoma." (PMID 35328764, 2022). "CCNE1 gain and RB1 loss could potentially impair actionability in some patients with high-grade serous carcinomas." (PMID 33947352, 2021). "Alterations of RB1 were more prevalent in high-grade serous carcinomas (P = 0.011)." (PMID 33947352, 2021). "Co-expression of all three markers (Rb1, P16 and ER) was seen in 10, 10, 6 and 0 % of high grade serous carcinoma (HGSC), low grade serous carcinoma (LGSC), endometrioid carcinoma (EC) and mucinous carcinomas, respectively." (PMID 26043844, 2015).
thyroid cancer (10 papers, 2011 to 2025). "For instance, we found an increased incidence in the loss of chromosome 13q (harbouring RB1) with age in thyroid cancer." (PMID 33879792, 2021).